CALHM1 (calcium homeostasis modulator 1)
Description:
Pore-forming subunit of gustatory voltage-gated ion channels required for sensory perception of sweet, bitter and umami tastes (By similarity). With CALHM3 forms a fast-activating voltage-gated ATP-release channel in type II taste bud cells, ATP acting as a neurotransmitter to activate afferent neural gustatory pathways (By similarity). Acts both as a voltage-gated and calcium-activated ion channel: mediates neuronal excitability in response to membrane depolarization and low extracellular Ca(2+) concentration. Has poor ion selectivity and forms a wide pore (around 14 Angstroms) that mediates permeation of small ions including Ca(2+), Na(+), K(+) and Cl(-), as well as larger ions such as ATP(4-). Mediates Ca(2+) influx and downstream activation of the ERK1 and ERK2 cascade in neurons. Triggers endoplasmic reticulum stress by reducing the Ca(2+) content of the endoplasmic reticulum. May indirectly control amyloid precursor protein (APP) proteolysis and aggregated amyloid-beta (Abeta) peptides levels in a Ca(2+)-dependent manner.
Synonyms: FAM26C
Tractability: Small molecule: a structure with a bound ligand is known. Antibody: its Gene Ontology location is reachable by antibodies, with high confidence; UniProt places it where antibodies can reach, with medium confidence; UniProt predicts a signal peptide or a membrane-spanning region.
Gene: Protein-coding gene on chromosome 10 (103,453,240 to 103,458,900, reverse strand). Ensembl gene ENSG00000185933.
Subcellular location: Cell membrane; Endoplasmic reticulum membrane; Basolateral cell membrane
Pathways (Reactome):
Sensory Perception: Sensory perception of salty taste; Sensory perception of sweet, bitter, and umami (glutamate) taste
Gene Ontology:
Molecular function: calcium-activated cation channel activity; identical protein binding; protein binding; voltage-gated monoatomic ion channel activity; monoatomic cation channel activity; voltage-gated calcium channel activity; voltage-gated channel activity
Biological process: ATP export; monoatomic cation transport; protein homooligomerization; regulation of monoatomic ion transmembrane transport; ATP transport; sensory perception of bitter taste; sensory perception of sweet taste; sensory perception of umami taste; calcium ion transmembrane transport; monoatomic cation transmembrane transport; monoatomic ion transmembrane transport; protein heterooligomerization; sensory perception of taste; transmembrane transport
Cellular component: endoplasmic reticulum membrane; plasma membrane; basolateral plasma membrane; plasma membrane raft
Genetic constraint (gnomAD): Loss-of-function variants: 14 observed, 16.92 expected, observed/expected ratio (o/e) 0.83, 90% interval 0.55 to 1.29. The upper end of that interval is the gene's LOEUF score, 1.29, which puts it in group 5 of 6, group 1 being the genes least tolerant of losing a copy. Missense variants: 458 observed, 517.54 expected, observed/expected ratio (o/e) 0.88, 90% interval 0.82 to 0.96. Synonymous variants: 215 observed, 226.57 expected, observed/expected ratio (o/e) 0.95, 90% interval 0.85 to 1.06.
Homologues: Orthologues: chimpanzee CALHM1 (99% identical), macaque CALHM1 (98% identical), rabbit CALHM1 (95% identical), dog CALHM1 (94% identical), pig CALHM1 (93% identical), mouse Calhm1 (92% identical), rat Calhm1 (91% identical), guinea pig CALHM1 (90% identical), tropical clawed frog calhm1 (66% identical), zebrafish calhm1a (56% identical), zebrafish calhm1b (53% identical), Caenorhabditis elegans clhm-1 (17% identical). Paralogues in human: CALHM3 (43% identical), CALHM2 (25% identical), CALHM4 (21% identical), CALHM6 (21% identical), CALHM5 (17% identical).
Diseases named in the same sentence as CALHM1 in open-access papers:
CALHM1 is named in the same sentence as 15 diseases in open-access papers, as found by Europe PMC text mining. Sharing a sentence is not in itself a finding about the gene and the disease. The quoted sentences say what the papers report.
Alzheimer disease (10 papers, 2009 to 2025). A progressive, neurodegenerative disease characterized by loss of function and death of nerve cells in several areas of the brain leading to loss of cognitive function such as memory and language. "Rare variants in CALHM1 are also found to be associated with early onset of Alzheimer’s disease by regulating Ca2+ homeostasis." (PMID 34408668, 2021). "A nonsynonymous polymorphism in the CALHM1 gene, P86L, was found to influence the age at onset of Alzheimer’s disease, possibly by altering amyloid beta peptide levels." (PMID 29534490, 2018). "The mutated form of the Ca2+ channel CALHM1 (Ca2+ homeostasis modulator 1), P86L‐CALHM1, has been correlated with early onset of Alzheimer's disease (AD)." (PMID 26416646, 2015). "Calcium homeostasis modulator 1 (CALHM1) is a protein responsible for causing Alzheimer’s disease." (PMID 35741655, 2022). "Recent studies indicated that calcium homeostasis modulator 1 (CALHM1) contributes to Alzheimer's disease by regulating the excitability of neurons in the cerebral cortex." (PMID 40612234, 2025). "As a result, additional research and analysis of CALHM1 function in Alzheimer’s disease will be aided." (PMID 35741655, 2022). "The absence of an experimentally characterized structure has hampered progress in determining the function of CALHM1 in Alzheimer’s disease." (PMID 35741655, 2022). "CALHM1 is a plasma membrane voltage-gated Ca2+-permeable ion channel that controls amyloid-β (Aβ) metabolism and is potentially involved in the onset of Alzheimer's disease (AD)." (PMID 25386646, 2014). "The identification of several modulators of calcium homeostasis, such as presenilins and CALHM1, as potential factors involved in the pathogenesis of Alzheimer's disease, provides strong support for a role of calcium in neurodegeneration." (PMID 19419557, 2009). "CALHM1 (calcium homeostasis modulator 1) is involved in the pathogenesis of Alzheimer’s disease." (PMID 35741655, 2022). "In 2008, CALHM1, previously termed FAM26C, was discovered in a bioinformatics search for human genes preferentially expressed in the hippocampus and located in the susceptible loci of Alzheimer’s disease." (PMID 29534490, 2018).
amnesia (1 paper, 2016). Pathologic partial or complete loss of the ability to recall past experiences ( AMNESIA, RETROGRADE) or to form new memories ( AMNESIA, ANTEROGRADE). "This would suggest that CALHM1 loss-of-function in these brain regions might contribute to episodic amnesia at the early stages of AD pathogenesis." (PMID 27066908, 2016). "For example, it will be important to investigate whether CALHM1 deficiency leads to an increase in Aβ levels in brain regions affected by episodic amnesia, such as the medial temporal or frontal lobes." (PMID 27066908, 2016).
brain ischemia (1 paper, 2020). Diminished or absent blood supply to the brain caused by obstruction (thrombosis or embolism) of an artery resulting in neurologic damage. "The unique Ca2+ permeation of CALHM1 relates to the molecular events that take place in brain ischemia, such as depolarization and extracellular changes in [Ca2+]e, particularly during the reperfusion phase after the ischemic insult." (PMID 32182953, 2020). "In this context, we aimed to identify by which molecular mechanisms the absence or blockade of CALMH1 exerts a protective effect under brain ischemia conditions by using hippocampal slices of Calhm1+/+, Calhm1+/−, and Calhm1−/− mice." (PMID 32182953, 2020). "In cortical neurons transfected with an shRNA-CALHM1 showed a 13% reduction in lactate dehydrogenase release, indicating a mild contribution of CALHM1 to brain-ischemia neurotoxicity." (PMID 32182953, 2020). "Upon OGD/Reox, the partial lack of CALHM1 exerts neuroprotective properties, pointing out that the possibility of only the deletion of one allele of CALHM1 is enough to induce neuroprotection against brain ischemia." (PMID 32182953, 2020). "In the present work, we have shown that the partial or total absence of CALHM1 results neuroprotective against neuronal death in an ex vivo model of brain ischemia, mice hippocampal slices subjected to OGD/reox." (PMID 32182953, 2020). "Due to the fact that the absence of CALHM1 proved to be neuroprotective in the OGD/Reox model, new experiments were performed, but this time focusing on the neurotransmitter glutamate, known to be cytotoxic during brain ischemia." (PMID 32182953, 2020).
chronic rhinosinusitis (1 paper, 2017). Chronic form of sinusitis. "The presence of CALHM1 in the airway, and its proposed role in mechanical signal transduction, has important implications for understanding regulation of mucociliary clearance and its dysregulation in diseases such as chronic rhinosinusitis." (PMID 28751666, 2017).
cognitive deficits (1 paper, 2016). "In the context of the present work, future studies will have to determine whether the observed cognitive deficits in Calhm1−/− mice are mediated, at least in part, by a deregulation in Aβ homeostasis." (PMID 27066908, 2016).
epilepsy (1 paper, 2025). A brain disorder characterized by episodes of abnormally increased neuronal discharge resulting in transient episodes of sensory or motor neurological dysfunction, or psychic dysfunction. "In summary, our results identify CALHM1 as a new contributor to seizures and suggest targeting of CALHM1 as new treatment strategy for epilepsy." (PMID 40601217, 2025). "While our results highlight a previously unrecognized role for CALHM1 in modulating seizure severity, further studies in chronic epilepsy models are needed to define its precise function in epileptogenesis." (PMID 40601217, 2025). "Interestingly, CALHM1 protein levels seem to be downregulated in the hippocampus in epilepsy (mice and humans)." (PMID 40601217, 2025). "To test whether CALHM1 protein levels are altered following SE and in epilepsy, we analyzed ipsilateral hippocampal tissue from mice subjected to IAKA-induced SE shortly following SE and once epilepsy was established." (PMID 40601217, 2025). "Moreover, future experiments should be designed to establish the mechanisms of action (e.g., cell-type specific expression and activation of CALHM1, CALHM1-dependent changes in intracellular Ca2+/eATP) and its role during different pathological contexts (i.e., acute seizures vs epilepsy)." (PMID 40601217, 2025). "While no change in CALHM1 protein levels was observed 8 h and 24 h post-SE, CALHM1 protein levels were reduced 4 weeks post-IAKA, time-point when epilepsy is usually well-established in the IAKA model." (PMID 40601217, 2025).
ischemia (1 paper, 2020). A hypoperfusion of the BLOOD through an organ or tissue caused by a PATHOLOGIC CONSTRICTION or obstruction of its BLOOD VESSELS, or an absence of BLOOD CIRCULATION. "Taken together, we can conclude that genetic or pharmacological inhibition of CALHM1 results in a neuroprotective effect against ischemia, due to an attenuation of the neuronal calcium overload and downregulation of oxygen reactive species production." (PMID 32182953, 2020). "Focusing on our results, CALHM1 absence results in high cell viability upon exposure of hippocampal slices to ischemia-related protocols and less ROS production in the CA1 hippocampal region." (PMID 32182953, 2020).
memory impairment (1 paper, 2020). "A recent study demonstrated that CALHM1 deficiency in mice leads to cognitive and neuronal deficits, which manifest memory impairment and hippocampal long-term potentiation (LTP), pointing to CALHM1 as a potential treatment target in AD." (PMID 33233678, 2020).
neuroblastoma (1 paper, 2021). Neuroblastoma (NB) is the most common solid, extracranial childhood tumor. "In neuroblastoma cells, 20-30 μM CALHM1 significantly inhibited toxicity effect induced by Ca2+ influx through CALHM channels by 80%." (PMID 34408668, 2021). "CGP 37157 inhibited Ca2+ influx through CALHM1 channels at low concentrations in neurons; 0.1-10 μM of CGP 37157 resulted in 50% inhibition of Ca2+ influx through CALHM1 in neurons and neuroblastoma cells." (PMID 34408668, 2021).
Onset (1 paper, 2013). The age group in which disease manifestations appear. "To investigate the role of CALHM1 variants in early-onset AD (EOAD), we sequenced all CALHM1 coding regions in three independent series comprising 284 EOAD patients and 326 controls." (PMID 24069280, 2013).
status epilepticus (1 paper, 2025). Status epilepticus is defined as a continuous seizure lasting more than 30 min, or two or more seizures without full recovery of consciousness between any of them. "Here, we tested if the pharmacological blocking of CALHM1 via CGP37157 (7-chloro-5-(2-chlorophenyl)-3,5-dihydro-4,1-benzothiazepin-2-(1H)-one) alters the severity of intra-amygdala kainic acid-induced status epilepticus." (PMID 40601217, 2025).
temporal lobe epilepsy (1 paper, 2025). A localization-related (focal) form of epilepsy characterized by recurrent seizures that arise from foci within the temporal lobe, most commonly from its mesial aspect. "In addition, CALHM1 protein levels are down-regulated in the hippocampus in epileptic mice and Temporal Lobe Epilepsy (TLE) patients." (PMID 40601217, 2025).
cancer (1 paper, 2022). A tumor composed of atypical neoplastic, often pleomorphic cells that invade other tissues. "It has been reported that PANX1, ABC, CALHM1, VRACs, and MACs can regulate TME via ATP release channel modulation in order to exert therapeutic effects against cancer." (PMID 36291937, 2022).
respiratory diseases (1 paper, 2021). "More studies are needed to define the functional role of CALHM1 and CALHM2 in sustained pulmonary vasoconstriction and vascular stiffen in the development of PAH and PH due to respiratory diseases and/or hypoxia." (PMID 34408668, 2021).
CALHM1 also shares sentences with these, for which no sentence is quoted: hippocampal atrophy (1 paper).